H19 (H19 imprinted maternally expressed transcript)
Diseases named in the same sentence as H19 in open-access papers (continued):
Sharing a sentence is not in itself a finding about the gene and the disease.
cancer (continued). "Accumulating evidence has shown that lncRNAs drive cancer metabolic reprogramming by directly or indirectly interacting with key metabolic enzymes and regulatory molecules, further altering related metabolites and disrupting multiple metabolic pathways, including lncRNAs H19, NBR, and PVT1." (PMID 40831535, 2025). "Our results add to the body of evidence suggesting that expression of different H19 isoforms in cancer may be regulated by different mechanisms, some of which lead to LOI and biallelic isoform expression, whereas others may upregulate monoallelically expressed isoforms." (PMID 40414875, 2025). "The impact of H19 on the metastatic abilities of human BC cells could be due to the sponging of miRNAs, such as regulating members of the let-7 miRNA family, which all play important roles in development, glucose metabolism, and cancer." (PMID 38773429, 2024). "Moreover, although H19 is highly expressed in most cancers and has carcinogenic functions, it may play a dual role in cancer." (PMID 38355574, 2024). "In addition to the miRNA regulatory network, H19, functioning as a ceRNA, constitutes another RNA intermolecular regulatory model that involves a broader set of genes and a more extensive regulatory network for regulating PCDs in cancer." (PMID 38355574, 2024). "As a result of H19’s involvement, several Iso_mRNAs were integrated into the subgraph, leading to the enrichment of coding genes in NeOModuleH19(1.5) not just in hsa05206 but also in two novel pathways, namely the hsa05200 cancer pathway and the hedgehog signaling pathway hsa04340." (PMID 39202109, 2024). "However, the detailed molecular mechanism behind the direct interactions between pre-miR-675 and RBP or its parent H19 lncRNA is currently unknown, specifically during cancer progression." (PMID 37624037, 2023). "However, the biological function of H19 in cancers, including HCC, remains controversial." (PMID 37744274, 2023). "Hence, increasing drug sensitivity and decreasing cancer cells drug resistance might be realized by targeting H19." (PMID 36246634, 2022). "In vivo experiments showed that H19-DTA could suppress the growth of multiple cancer types." (PMID 35565245, 2022). "Moreover, the interactive mechanism between ferritin and H19 differs in different cancer cells." (PMID 36246634, 2022). "Notably, H19 is the first discovered eukaryote lncRNAs with a relatively high evolutionary conservancy in humans and mice, and plays an essential role in human embryonic development and diverse conditions, including invasive cancers and fibrotic diseases." (PMID 36010635, 2022). "Further investigations would also be required to better understand the molecular mechanisms associated with the upregulation of these PCAN lncRNAs in cancer and to assess whether they could constitute potential pan-cancer therapeutic targets as well as imprinted oncofetal genes similar to H19." (PMID 35729321, 2022). "In addition to cancer-derived EVs, lncRNA H19 is also found in EVs of tumor stromal cells." (PMID 33920605, 2021). "In addition, H19 plays an integral role in evolution of several types of cancer." (PMID 34081618, 2021). "H19 may play a role as a cancer-promoting factor in gastrointestinal tumors." (PMID 34922547, 2021). "Therefore, alterations in the imprinted lncRNA H19, essential for differentiation and growth-related pathways, may result in different effects in cancer cells." (PMID 34526543, 2021). "However, its role in cancer initiation, progression and metastasis remain controversial and the lncRNA H19 may act as an oncogene during tumorigenesis, being one of the key genes in cancer development." (PMID 34526543, 2021). "Moreover, high H19 expression may be a molecular marker to predict cancers and prognoses after clinical treatment, including the rate of post-therapeutic relapse in hematological cancer patients." (PMID 34760887, 2021).
cancer (continued). "Additionally, abnormal H19 overexpression is thought to be involved in the development and progression of cancer in many systems of human body, such as the digestive system, the respiratory system, the breast, the genitourinary system, the nervous system, and others." (PMID 34421359, 2021). "The lncRNA H19 is highly expressed in embryonic tissue and placenta and repressed after birth, but is highly re‐expressed in multiple cancers including both hematopoietic and solid tumors including breast, esophageal, bladder, lung, and endometrial and cervical cancers." (PMID 32146726, 2020). "Furthermore, reduced expression of H19 can inhibit cancer development." (PMID 33680956, 2020). "Current studies have shown that H19 predominantly acts as a sponger of miRNAs, including miRNA138, miRNA200 and others to enhance the expression of their targeted genes in a context and cell-specific manner, dependent on the cell type and status in different types of cancers." (PMID 32272875, 2020). "In addition, H19 also regulates drug resistance of several types of malignant tumors." (PMID 32272875, 2020). "However, we observed an opposite expression in AT compared to cancer cells, suggesting a different role of this lncRNA in visceral adipocytes, that could potentially involve H19 target genes STAT3 and SPARC." (PMID 32714872, 2020). "H19 is closely linked to insulin-like growth factor-2 (IGF2) gene which is also located in the region subjected to imprinting by methylation and plays a crucial role in the normal growth and development of the fetus and also important in cancer occurrence and progression." (PMID 32509581, 2020). "However, the mechanistic insights of deregulated H19 expression in cancer are limited." (PMID 33267897, 2020). "Notably, lncRNA H19 is frequently over-expressed in the majority of human cancers including CRC." (PMID 31164794, 2019). "Upon exposure to oxaliplatin, CAFs may release exosomes containing long noncoding RNA (lncRNA) H19 to cancer cells, which has competing endogenous RNA potential for miR-141, a tumor suppressor miRNA that targets β-catenin and suppresses the Wnt/β-catenin pathway." (PMID 31885581, 2019). "The pooled results in the present study were sensitivity of 0.69 (95%CI=0.62-0.76), specificity of 0.79 (95%CI=0.70-0.86), and the AUC of0.79 (95%CI=0.76-0.83), suggesting that H19 may be a potential biomarker to discriminate cancer patients from normal people." (PMID 31016202, 2019). "However, H19 was found to be highly expressed in a variety of cancers." (PMID 31752724, 2019). "Therefore, we hypothesized that functional SNPs of H19 might influence the physiological function of H19 or the expression of cancer-related genes, thereby contributing to the development of OSCC." (PMID 29844862, 2018). "Moreover, the knockdown of H19 could significantly suppress hypoxia-induced cancer cell proliferation in vivo." (PMID 30071841, 2018). "A recent meta-analysis showed that H19 expression might be a novel molecular marker for predicting prognosis and could also be a predictive factor of clinicopathological features in various cancers." (PMID 29643943, 2018). "The working mechanisms of H19 in cancer can be either epigenetic or post-transcriptional, the former involving the interaction with one or more epigenetic protein modulators, while in the latter H19 sponges specific miRNAs, with a consequent specific target de-repression." (PMID 29643989, 2018). "We next investigated whether H19 mediated E2-derived cancer stem-like traits in PTC cells." (PMID 30389909, 2018). "Moreover, the inhibition of H19 represents a potential candidate for cancer therapies." (PMID 30154386, 2018). "Recently, a meta-analysis for the association of H19 polymorphisms and cancer risk had published, but the interaction of H19 SNPs and environmental factors as well as the association of H19 SNPs and the cancer prognosis were not analyzed further." (PMID 29511035, 2018).
cancer (continued). "Taken together, H19 exerted its molecular function in order to regulate the expression of related genes, which may affect carcinogenic signaling pathways, thereby promoting the progression of malignant carcinoma." (PMID 30219045, 2018). "However, the prognostic value of H19 in female-specific cancers has remained uncharacterized." (PMID 27926484, 2017). "In conclusion, our studies extend the known mechanisms by which metformin can exert its effects on gene expression in cancer cells, and demonstrate for the first time that metformin is able to directly impact cancer cell proliferation by altering DNA methylation via regulation of the H19/SAHH axis." (PMID 27775072, 2017). "However, the mechanisms by which H19 promotes cancer progression are not well understood; in particular, the molecular mechanisms by which H19 regulates CRC proliferation are unknown." (PMID 28164117, 2017). "However, there is still controversy about whether H19 expression can predict the prognosis of certain cancers." (PMID 27926484, 2017). "However, the relationship between H19 expression and other cancers might need more studies to illuminate." (PMID 27672656, 2016). "Therefore, our study demonstrated that H19 might be a predictive factor for assessing progression and metastasis in cancers." (PMID 27672656, 2016). "Therefore, H19 could serve as a potential marker for progression and metastasis evaluation of cancers." (PMID 27672656, 2016). "Thus, abundant lncRNAs such as H19, Urothelial Carcinoma Associated 1 (UCA1), HOTAIR, MALAT1, and HIF1A-antisense transcript (HIF1A-AS) are attractive as potential biomarkers and/or therapeutic targets in cancer." (PMID 26590207, 2016). "LncRNA H19 may play a significant role in cancer occurrence and development." (PMID 27825121, 2016). "The development of cancer may be promoted by the up-regulated expression of H19." (PMID 27825121, 2016). "Thus, it is biologically conceivable that the loss of miR-24 function owing to a SNP rs2839698 in the 3′ UTR of H19 may give rise to overexpression of H19 and thereby promote proliferation, migration and invasion of some cancer cells." (PMID 27732938, 2016). "Our meta-analysis suggests that the lncRNA H19 rs217727 polymorphism might not be associated with overall cancer risk." (PMID 27486980, 2016). "In the current study, we identified 24 differentially expressed lncRNAs in NPC including GAS5, NEAT1 and H19, which contribute to the development and progression of cancers and might serve as novel, non-invasive biomarkers for cancer diagnosis, progression and prognosis." (PMID 26246469, 2015). "However, the association between H19 genetic variation and risk of cancer in the Chinese Han population has not previously been reported." (PMID 25944697, 2015). "Moreover, H19 has been demonstrated to be functionally important in several human cancers." (PMID 27077133, 2015). "However, numerous studies have shown that H19 is an oncogene in many types of cancers." (PMID 26353930, 2015). "Hence, a double promoter DTA-expressing vector was created, carrying on a single construct two separate genes expressing the diphtheria toxin A-fragment (DTA), from two different regulatory sequences, selected from the cancer-specific promoters H19 and IGF2-P4." (PMID 21162716, 2010). "However, H19 is either highly expressed and/or manifest an aberrant allelic pattern of expression in over 30 types of cancer, suggesting that H19 may play a role in tumorigenesis." (PMID 17786216, 2007). "Moreover, H19 is highly expressed in liver metastasis derived from a range of carcinomas." (PMID 17786216, 2007). "Mechanically, H19 can exert its carcinogenic effects by activating autophagy, inhibiting apoptosis, and enhancing EMT, thus increasing the aggressiveness of cancer cells." (PMID 40028033, 2025).
cancer (continued). "However, since the discovery of H19 in 1980 and Xist in 1990, increasing evidence has shown that lncRNAs regulate gene expression at epigenetic, transcriptional, and post-transcriptional levels through specific regulatory actions and are involved in the development of cancer and other diseases." (PMID 39937018, 2025). "Such genes showed a lower proportion of monoallelic vs biallelic expression in cancer cell lines than some other imprinted genes, e.g., SNRPN, SGCE, NLRP2, H19, and ANO1." (PMID 40414875, 2025). "In terms of mechanisms, the knockdown of H19 decreased the phosphorylation of PI3K and AKT, consistent with the inhibition of this survival signaling pathway, which is significant for cancer cell proliferation and resistance to cell death." (PMID 41154428, 2025). "We observed tissue-specific and isoform-specific expression patterns of multiple imprinted genes in cancer cell lines that were consistent with previous reports of such patterns, e.g., LOI of H19." (PMID 40414875, 2025). "These lncRNAs, which include MALAT1, H19, HOTAIR and others, have been found to be important contributors to the development and spread of cancer." (PMID 39912983, 2025). "Thus, targeting H19 may overcome the chemotherapy resistance in various cancers." (PMID 39940704, 2025). "In non-small lung cancer (NSCLC) cell lines (A549 and H1650), hypoxia induces the expression of lncRNAs H19, HIF1-α, HO-1, MRP-1 and P-gp, resulting in increased migration and invasion of cancer cells along with an increase in cisplatin resistance." (PMID 39940704, 2025). "Silencing of H19 was found to reduce invasion and migration in the HEC-1-B cancer cell line, while also leading to a decrease in Snail expression and an increase in E-cadherin expression." (PMID 38166752, 2024). "Recent studies have reported a positive correlation between H19 and the PI3K/Akt pathway, which regulates apoptosis and autophagy in various cancer types." (PMID 38355574, 2024). "High expression levels of LincRNA H19, miR-675, MRP3, HOXA1, and MMP16 in cancer tissues correlated with advanced disease stages and poorer survival rates." (PMID 39267845, 2024). "Downregulation of H19 by metformin promoted ferroptosis in MCF-7 cells by increasing ROS production and decreasing reduced Glutathione (GSH) levels in the cancer cells." (PMID 40176927, 2024). "Interestingly, H19 may interfere with the activity of the telomerase complex in cancer cells." (PMID 38773429, 2024). "In the same context, relevant reports have shown that lncRNAs H19, MEG3, CPS1-IT1, and lnc010561 also display biological interactions with melatonin in cancer which are related to apoptosis, pyroptosis, and metastasis." (PMID 36332600, 2023). "Analysis of the Biogrid database revealed that ILF2-interacting proteins are mostly enriched in the DDR signaling pathway, which further supports that the involvement of H19 and ILF2 in the DNA damage response of cancer cells." (PMID 37298108, 2023). "There is also emerging evidence that long noncoding RNAs such as lncRNA H19, lncRNA NEAT1, lncRNA miR210HG and lncRNA DCST1-AS1 act as sponges for miR-874, suppressing miR-874 expression and contributing to cancer progression." (PMID 36323841, 2022).
cancer (continued). "Thus, H19 could regulate the progression of cancer by changing the expression of IGF2." (PMID 36246634, 2022). "LncRNAs, such as HOTAIR, H19, LncTCF7, LUCAT1, MALAT1, LINC00511, and FMR1-AS1, have been described as key regulators of stemness in cancer, allowing cancer cells to acquire this phenotype." (PMID 35954194, 2022). "Increased lncRNA H19 expression induced the tamoxifen and fulvestrant resistance in ETR cancer cells." (PMID 36685962, 2022). "Several lncRNAs involved in the local repression of imprinted loci also show significant deregulation in cancer, including KCNQ1OT1, H19, and maternally expressed gene 3 (MEG3), which are frequently overexpressed in a wide range of cancer types." (PMID 34668345, 2022). "MALAT1, HOTAIR, H19, HOTTIP, ANRIL, and NEAT1 are among the most famous lncRNAs which have been mostly studied in many types of cancer exhibiting dysregulation in cancer cells, tissues and body fluids of affected patients." (PMID 35281110, 2022). "Some of the lncRNA with good potential in cancer diagnosis or prognosis include PCA3, MALAT1, HOTAIR, H19, and CCAT1." (PMID 35892331, 2022). "Therefore, H19 may be a potential target for cancer therapy." (PMID 34644456, 2022). "Mechanically, H19 acts as a sponge of miR-615-3p, which in turn represses ATG7 translation, an oncogenic protein involved in autophagy response of different types of carcinomas." (PMID 35955440, 2022). "H19 is an imprinted oncofetal gene that is located close to the IGFII gene locus, and its role in cancer has been widely studied." (PMID 33236528, 2021). "In the following sections, we will review and highlight the characteristics and functions of some of the lncRNAs, i.e., HOTAIR, NEAT1, H19, MALAT1, and MEG3, frequently involved in several female-oriented cancers." (PMID 34885213, 2021). "Their high specificity allows for the detection of cancer initiation (e.g., SPRY4-IT1), progression (e.g., ATB), metastasis (e.g., LINC00461, CCAT2 and H19) and response to therapy (e.g., MALAT1 or HOTAIR)." (PMID 34072257, 2021). "Among them, lncRNAs PVT1, H19, and UCA1 were proved to involve in gemcitabine resistance in other cancers and CCA progression, suggested that our screen strategy for gemcitabine resistance-related lncRNAs were feasible." (PMID 33436545, 2021). "Aberrant expression patterns for H19, MALAT1, TP73, ZEB1-AS1, SNHG15, and others were detected in a multitude of other cancer types, as well as in relation to other molecules belonging to the microRNA-200 family." (PMID 35011635, 2021). "The relationship between H19 and the JAK/STAT signaling pathway has been elucidated in several cancers, and the detailed mechanisms are described in the following sections." (PMID 34977037, 2021). "Recently, a large number of studies have reported a positive correlation between H19 and the PI3K/Akt pathway in various types of cancer, suggesting a promising therapeutic target for cancer treatment." (PMID 34977037, 2021). "It was also addressed that lncRNA-H19 imprinted maternally expressed transcript (lncRNA-H19) reinforces EMT and metastasis in diverse types of cancer." (PMID 33435156, 2021). "H19 is the first functionally characterized lncRNA in DIPG and a promising therapeutic candidate for treating this incurable cancer." (PMID 34502082, 2021). "In conclusion, our study has shown that lncRNA, H19 was up-regulated in serum-derived exosomes from advanced-stage CRC, while exosomal LINC00152 was down-regulated in CRC as compared with non-cancer individuals." (PMID 34571795, 2021). "Here, we review the research approaches to understanding the regulatory role of H19 and potential mechanisms in the progression of PDAC and other types of cancers and diseases." (PMID 32272875, 2020). "H19 can interact with the PRC2 complex, such as by binding to the enhancer of Zeste 2 polycomb Repressive complex 2 subunits (EZH2) in cancer cells." (PMID 33193379, 2020).